SLC2A1 (solute carrier family 2 member 1)
Diseases named in the same sentence as SLC2A1 in open-access papers (continued):
Sharing a sentence is not in itself a finding about the gene and the disease.
tumor (continued). "However, both SLC2A1 (FDR < 0.01) and SLC2A3 (FDR < 0.001) genes—associated with higher glucose uptake and oncogenic growth —are markedly overexpressed in BRAF- (vs RAS)-like tumours." (PMID 37198319, 2023). "Interestingly, the expression of ECT2, FGD6, MMP14, and SLC2A1 were statistically different in the patients with different tumor stage, which implied that ECT2, FGD6, MMP14, and SLC2A1 might be associated with the development of PC." (PMID 37604837, 2023). "However, in ESCA and OV, SLC2A1 showed a decrease in expression with increasing tumor stage, which appeared contradictory to the results of our analysis and may require further study." (PMID 36712872, 2022). "In order to explore the clinical significance and prognostic value of SLC2A1, we utilized massive databases to conduct an in-depth exploration of the methylation of SLC2A1, and we also investigated the differences in immune infiltration between tumor and normal tissues." (PMID 36065306, 2022). "Therefore, we further explored the link between SLC2A1 and tumor immunity." (PMID 36712872, 2022). "Thus, SLC2A1 may promote tumor proliferation and metastasis by affecting neutrophils and CAFs in the TME." (PMID 36358765, 2022). "SLC2A1 encodes the glucose transporter, which is associated with the abnormal metabolism during cancer cell invasion, while SLC8A1 participates in the migration of tumor cells via regulating Na+/Ca2+ exchange, it is also involved in the endometrial tissue cellular heterogeneity." (PMID 34692538, 2021). "When Slc2a1 was excised after the cells had grown as tumors in vivo (i.e., when cells were cultured from control tumors and then treated with Cre recombinase), a decrease in tumor growth rates and glucose uptake was observed in the absence of GLUT1, but tumors formed." (PMID 27998284, 2016). "The tumors from the NIC-GLUT1F/+ mouse expressed Cre and GLUT1, suggesting that, in this mouse, Slc2a1 haplo-insufficiency did not occur, and that there may have been early changes in tumor metabolism that overcame the loss of one Slc2a1 allele." (PMID 27998284, 2016). "We identified a TTF-1/p40-negative tumor cell population with a hybrid adenocarcinoma-squamous expression pattern and upregulation of SLC2A1 (GLUT1)." (PMID 41571939, 2026). "When analyzing the clinical relevance of SLC2A1 in LUAD, we observed significant variations in its expression across tumor stages." (PMID 40276602, 2025). "The volcano plot showed high expression of tumor markers such as SLC2A1 and BCL2L1 in E4, suggesting a strong proliferative advantage and anti-apoptotic ability in tumor progression." (PMID 40463392, 2025). "In our study, we detected a significant overexpression of SLC2A1 in 22 out of 33 human cancer tissues, while MPST was upregulated in 13 out of 33 tumor tissues." (PMID 40746529, 2025). "We also found that FGFR4 and related metabolic genes (SLC2A1, LDHA, PFKL) were upregulated in tumors and FGFR4 high-expression groups, suggesting FGFR4's role in tumor metabolism." (PMID 40091020, 2025). "Mis-localization of SLC2A1 to lysosomes can affect glucose uptake, thereby activating the AMPK-ULK1 pathway, sensitizing cancer cells to energy stress, and inhibiting tumor growth." (PMID 40092704, 2025). "Overall, AGER, PECAM1, and SLC2A1 were validated for their expression in normal and LUAD tumor IHC samples, showing that the candidate gene biomarkers can function as biologically significant biomarkers to aid in the detection of early-stage LUAD." (PMID 40563443, 2025). "Significant overexpression of SLC2A1, SLC2A5, and SLC2A11 across various tumor types, including LUAD." (PMID 40824962, 2025). "In vitro and in vivo experiments showcased that SLC2A1 inhibition significantly hampered LUAD A549 cell proliferation, migration, and invasion capabilities, as well as tumor growth in nude mice." (PMID 40824962, 2025).
tumor (continued). "Immunohistochemical staining data from the HPA database further confirmed the higher expression of SLC2A1 and MPST in tumor tissues compared to adjacent normal endometrial tissues." (PMID 40746529, 2025). "Key proteins identified, including ANXA1, SLC2A1, S100A4, and NFKB1, contribute to tumour progression and the resistance phenotype." (PMID 40004024, 2025). "Mechanistically, senescent T cells exhibit upregulated glycolysis via SLC2A1/GLUT1 and SASP secretion (IL6/IL8), fostering tumor permissive microenvironments." (PMID 40781676, 2025). "It has been repeatedly observed that glucose transporter GLUT1/SLC2A1 and lactic acid transporter MCT1/SLC16A1, MCT2/SLC16A7, MCT4/SLC16A3 are upregulated in multiple tumor types and participate in tumor genesis and development." (PMID 38396064, 2024). "Overall, these findings suggested that RRM2, SLC2A1, DDIT4, and VDAC2 were potential oncogene, whereas PEBP1 and IL33 were candidate tumor suppressor genes." (PMID 39311766, 2024). "As we expected, RRM2, SLC2A1, DDIT4, and VDAC2 were significantly upregulated transcriptionally and translationally in tumor samples, whereas PEBP1 and IL33 are significantly reduced in tumorous tissues." (PMID 39311766, 2024). "To this end, we observed that the expression of both SLC2A1 and B4GALT1 was enriched in tumor tissue regions in the EC." (PMID 38517922, 2024). "This provides additional insight into the role of SLC2A1 in NSCLC progression, particularly in the context of the hypoxic tumor microenvironment." (PMID 39858431, 2024). "The expression levels of GAPDH, FSCN1, SLC2A1, FAM83A, PLEK2, and GJB3 all presented significant differences between tumor tissues and normal tissues." (PMID 38370379, 2024). "We observed that the expression levels of GLUT1 (SLC2A1) and the glycolytic rate-limiting enzymes HK2 and PFKP were increased in response to stress both in mRNA and protein levels in CRC cells and tumor tissues." (PMID 37151872, 2023). "Moreover, Se-PC PDT treatment may dilute tumor metabolism and proliferation by depressing the activity of the glucose transporter GLUT1 (gene Slc2a1) and the iron transport-related factors LCN2 (gene Lcn2) and transferrin (gene Trf), which reduce the synthesis of hemoglobin and inhibit ferroptosis." (PMID 37994159, 2023). "In order to adapt to Warburg effect, tumor cells will overexpress multiple transporters, such as GLUUT1, solute carrier family 2A member 1 (SLC2A1) and so on." (PMID 36579634, 2023). "Regarding the protein levels of these genes, SLC2A1, MMP14, TOP2A, ANLN, and SLC22A3 exhibited higher expression in tumor samples compared to normal samples." (PMID 37604837, 2023). "The glucose transporter isoform 1 (GLUT1; SLC2A1) has been reported to promote aggressive tumor growth for functioning as a key rate-limiting factor in transporting glucose into cancer cells." (PMID 37217516, 2023). "Some genes were differentially expressed not only between normal and tumor samples, but also in tumor samples (CDKN2A; Solute Carrier Family 2 Member 1, SLC2A1)." (PMID 37239416, 2023). "Glucose transporters include SLC2A1, SLC2A2, SLC2A3, and SLC2A4, and we found the expression of SLC2A1 was significantly upregulated in HCC tumor, contrast with that in adjacent non-tumor tissues (from TCGA Database)." (PMID 37443106, 2023). "From 1895 metastasis-related genes, they found that the expression of SLC2A1, CDCA8, ATG10, and HOXD9 was higher in HCC tumor tissue whereas the expression of TPM1 was lower." (PMID 37974228, 2023). "The expression of BMP4 and SLC2A1 were acquired by analyzing the TCGA-LIHC dataset, as well as by immunohistochemical analysis of the 40 pairs of human HCC samples and para-tumor tissues." (PMID 37443106, 2023). "Cells absorb glucose via GLUT1(SLC2A1), hypoxic cells release lactate through MCT4(SLC16A4), while tumor cells and endothelial cells absorb lactate through MCT1(SLC16A1)." (PMID 37795453, 2023).
tumor (continued). "Higher expressions of the genes involved in the Tumor Microenvironment Pathway, including ICAM1, SLC2A1, and TNC were found in the PMCs of the LCP group." (PMID 37649596, 2023). "The correlation between SLC2A1 expression level and CRC immune infiltration cell was analyzed by Tumor IMmune Estimation Resource (TIMER), Gene Expression Profiling Interactive Analysis (GEPIA), and TCGA database." (PMID 35399515, 2022). "Eventually, the relation between SLC2A1 and CRC tumor ferroptosis, immunofiltration, m6A modification, and ceRNA network was investigated, which provides a basis for the development of new therapeutic strategies." (PMID 35399515, 2022). "We also analyzed the ability of SLC2A1 expression to predict CRC by drawing ROC curves and found that SLC2A1 has high accuracy in predicting the outcomes of normal and tumor." (PMID 35399515, 2022). "Treatment with 32-134D also inhibited hypoxia-induced expression of SLC2A1, LDHA, ENTPD1, and CA9 mRNA, which play roles in both tumor metabolism and immune evasion (P < 0.05)." (PMID 35499076, 2022). "Reduced SLC2A1, ABCB1, MMP2, twist family bHLH transcription factor 1, and VEGFA expression in tumor cells; downregulation of HIF-1α." (PMID 35640930, 2022). "In our study, we found that SLC2A1 is highly expressed in LUAD, and was related to a poor prognosis in terms of OS, PFI, DSS, and DFI, so we took LUAD as the representative tumor in the GO, KEGG, and GSEA analyses of SLC2A1." (PMID 36358765, 2022). "In pancreatic ductal adenocarcinoma, YTHDC1 promotes the maturation of miR-30d, and miR-30d can suppress aerobic glycolysis by binding RUNX1, regulating SLC2A1 and HK1 expression, thus attenuation Warburg effect to inhibit tumor progression." (PMID 35022030, 2022). "Then, we used GEPIA to explore the gene expression correlation between LDHA and glycolysis markers, including GLUT-1 (also named SLC2A1) and HIF1A, which play critical roles in glycolysis and tumor microenvironment." (PMID 33902615, 2021). "The upregulated ACSL3, DDIT4, RRM2, and SLC2A1 with HR > 1 were considered as oncogenes, whereas the downregulated HERPUD1 and PEBP1 with HR < 1 were regarded as tumor suppressors." (PMID 34499810, 2021). "In the current study, we observed a correlation between high levels of inflammatory markers (NLR and CRP) and tumor expression of CA9 and SLC2A1, which further supports the interplay between hypoxia and inflammation in MPNST." (PMID 33810575, 2021). "Key hub genes SLC2A1, CDH3 and EFHD2 showed increased expression across the tumour stage and were correlated with poor survival, whereas decrease of FAM171A1, ONECUT1 and PHYHIPL was correlated with better survival." (PMID 34013637, 2021). "In the current study, we investigated the clinical significance of tumor expressions of HIF1A, VEGFA, CA9, and SLC2A1 assessed by IHC and markers of systemic inflammation (NLR and CRP) in pediatric patients with MPNST." (PMID 33810575, 2021). "The expression levels of SLC2A1, CDCA8, ATG10 and HOXD9 are higher in tumor samples and lower in normal tissue samples." (PMID 34116652, 2021). "Downregulation of HK2 or SLC2A1 dramatically impaired METTL3-induced cell proliferation and colony formation in vitro and tumor growth in vivo, which further supported HK2 and SLC2A1 (GLUT1) as critical target genes of METTL3 in CRC." (PMID 32245489, 2020). "Ectopic expression of HK2 or SLC2A1 partially restored the proliferation and colony formation ability of METTL3-knockout cells and tumor growth." (PMID 32245489, 2020). "Previous studies have found several essential nutrient transporters, such as the glucose transporter SLC2A1 and the amino acid transporters SLC1A5, SLC7A5, SLC6A14, SLC7A11, and SLC38A2, which are upregulated in cancer as tumor promoters." (PMID 32461965, 2020). "The glucose transporter SLC2A1 (GLUT1) was a low ATP CRISPRi hit in glycolytic conditions, and inhibiting SLC2A1 can decrease glycolysis and tumor growth." (PMID 32859923, 2020).
tumor (continued). "In particular, we found that TMEM30A regulates several migration-related genes including SUB1, SLC2A1, CTNNB1, ACTB, and CLTC during tumor migration, which further demonstrates the effectiveness of our proposed method." (PMID 28640862, 2017). "FDG is primarily transported by SLC2A1 and SLC2A3, which suggests that FDG uptake by tumor cells will be different depending on different expression levels of glucose transporters." (PMID 28978124, 2017). "Western blotting of 12 HNSCC tumours consistently showed a significantly positive correlation of GATA3 with HIF-1α and GATA3 with SLC2A1, a well-known HIF-1 target (Pearson’s correlation coefficient=0.65 and 0.64, respectively, P<0.05)." (PMID 28263977, 2017). "Another well-characterized SLC family member useful in functional imaging is SLC2A1 (GLUT1), a major glucose membrane transporter that is upregulated in tumor cells (glycolytic rates in tumors can be more than 30-fold higher than in normal cells)." (PMID 26106611, 2015). "The expression of three other genes was reduced 2-fold to 6-fold in tumor versus adjacent liver (p < 0.05, t test, df = 4), including a 3′ UTR insertion in SLC2A1 and intronic insertions in PHGDH and EFHD1." (PMID 23540693, 2013). "Furthermore, H. pylori-induced immune responses and the hypoxic conditions within the tumor niche activate HIF-1α, which collaborates with BRD4 to upregulate glycolysis-related genes such as Slc2a1 (Solute Carrier Family 2 Member 1) and Hk2 (hexokinase 2)." (PMID 41171531, 2026). "However, notably, in the AZD2014-treated tumours, the expression of the glucose transporter GLUT1 (also known as SLC2A1) remained high in Region A even though there was generally a reduction following AZD2014 treatment in Region B." (PMID 40019006, 2025). "SLC2A1 had no staining in the normal lung samples (0/3) but had strong expression in the 4/6 LUAD tumor cases." (PMID 40563443, 2025). "Based on these findings, we hypothesize that SLC2A1 may remodel the TME, suppress immune responses, and promote tumor progression." (PMID 40276602, 2025). "The absence of SLC2A1 markedly inhibits A549 cell proliferation, migration, and invasion, while SLC2A1 knockout significantly suppresses tumor formation in nude mice." (PMID 40824962, 2025). "IHC analysis also revealed that SLC2A1 had high staining in the LUAD tumor and had no staining in the normal lung, validating the upregulation of the gene in LUAD." (PMID 40563443, 2025). "Additionally, we identified key proteins, including ANXA1, SLC2A1, and PPIG, which contribute to the tumour progression and resistance phenotype." (PMID 40004024, 2025). "The specific mechanism may be related to SLC2A1, which can inhibit T cell function by increasing the infiltration of OPN+ macrophages, thereby creating an immunosuppressive microenvironment in tumor tissue and promoting tumor immune evasion." (PMID 40093009, 2025). "We propose that SLC2A1 may influence tumor growth and metastasis by modulating the G2M checkpoint and EMT while also regulating tumor metabolism through glycolysis and PI3K-AKT-mTOR signaling, enhancing tumor cell adaptability in hypoxic environments." (PMID 40276602, 2025). "The orchestration of aerobic glycolysis regulation involves transcription factors, wherein miR-30d modulates the expression of Solute carrier family 2 member 1(SLC2A1) and Hexokinase 1(HK1) via the transcription factor RUNX1, thereby restraining tumor progression." (PMID 39791162, 2025). "Research into findings tumor-specific untranslated regions (UTRs) that are GLUT1/SLC2A1-specific can allow for targeted tumor GLUT1 suppression without affecting other normal cells." (PMID 40563757, 2025). "We compared the methylation values of SLC2A1 and MPST between normal and tumor tissues." (PMID 40746529, 2025).
tumor (continued). "Additionally, branched-chain amino acid transaminase 1 (BCAT1) and solute carrier family 2 member 1 (SLC2A1)—genes known to promote cancer cell invasion and tumor immune infiltration, respectively—were also up-regulated in the Liver ECM group." (PMID 40852642, 2025). "Using the HPA, AGER, MGP, PECAM1, and SLC2A1, normal lung and LUAD tumor IHC staining was accessed." (PMID 40563443, 2025). "Our qRT‐PCR experiments further revealed that METTL3 may promote the glycolysis capacity of ESCA cells by upregulating the expression of glycolysis‐related genes SLC2A1, GPI, PFKL, PGK1, ENO1 and PKM, thus facilitating tumour cell proliferation and migration." (PMID 38429907, 2024). "On the other hand, the downregulation of SLC2A1 expression after CTTPPPD administration may inhibit tumor growth and metastasis by reducing glucose uptake and energy supply of tumor cells." (PMID 39275122, 2024). "In contrast, SLC2A1 KD in K562 cells showed no phenotype, and OE was deleterious in tumours and RPMI." (PMID 38605144, 2024). "Several studies have shown that solute carrier family 2 member 1 (SLC2A1) is overexpressed in the tumor tissues of LUAD patients and may be involved in tumor-igenesis." (PMID 37576511, 2023). "IHC staining of clinical HCC samples showed that SLC2A1 was high expression in tumor tissues in contrast with that in adjacent non-tumor tissues." (PMID 37443106, 2023). "METTL3 increased HK2 and SLC2A1(GLUT1) mRNA stability and transcription levels through an m6A-IGF2BP2/3-dependent mechanism, then activated CRC glucose metabolism to facilitate cell proliferation and tumor growth in vitro and in vivo." (PMID 37152066, 2023). "ST1926 treatment down-regulated a group of oncogenic proteins (SLC2A1, SLC25A6, CBX3, DEK, DDX39B) and up-regulated a group of presumably tumor-suppressing proteins (PEBP1, HspBP1); PADI2 and CMPK1, of unknown function in GBM, were also up-regulated." (PMID 37762371, 2023). "We found that SLC2A1 was highly expressed in tumor samples (P < 0.05), and the expression of the other five genes was not significantly different between tumor and normal tissues (P > 0.05)." (PMID 37072786, 2023). "This was further confirmed in vivo, as TRPM7KO tumor exhibited less SLC2A3 expression but not SLC2A1." (PMID 36878949, 2023). "In our study, we show that transcriptional levels of SLC2A1, SLC2A5 are upregulated and those of SLC2A3, SLC2A6, SLC2A9, SLC2A14 are downregulated in LUAD patients, supporting the role of SLC2A1, SLC2A5 as oncogenes and SLC2A3, SLC2A6, SLC2A9, SLC2A14 as tumor suppressor genes." (PMID 36518662, 2022). "In contrast, FANCD2, PTGS2, SLC2A1, and SQLE were higher in tumor compared to normal tissues." (PMID 36733386, 2022). "The anti-tumour effects of Rec8 are caused by downregulation of cell growth-related genes (G6PD, SLC2A1, NOL3, MCM2, SNAI1, and SNAI2) and also by upregulation of both apoptosis or migration inhibitors (Gadd45G and LDHA) and tumour inhibitors (PinX1, IGFBP3, and ETS2)." (PMID 36139540, 2022). "Indeed, the GPx2 KD tumor expressed notably higher levels of glucose transporter GLUT1 (SLC2A1), aldolase-A (ALDOA), phosphoglycerate kinase (PGK1), and lactate dehydrogenase A (LDHA) than in the control tumor." (PMID 35193955, 2022). "One study identifies SLC2A1 may be a crucial glucose transporter in LUAD patients as SLC2A1 mRNA and protein levels are elevated in LUAD patients, and its overexpression is a potential indicator for lower differentiated tumor grade and poor prognosis." (PMID 36518662, 2022). "We speculated that the overexpression of SLC2A1 promoted the infiltration of neutrophil in CRC and ultimately played an important role in promoting tumor proliferation." (PMID 35399515, 2022). "SLC2A1, SLC2A5, SLC2A10, and SLC2A11 levels tended to be higher in patients with advanced tumor stages, which shows that these molecules may be involved in the development of malignancies in LUAD patients." (PMID 36518662, 2022).